TRIM56 (tripartite motif containing 56)
Diseases named in the same sentence as TRIM56 in open-access papers (continued):
Sharing a sentence is not in itself a finding about the gene and the disease.
cancer (12 papers, 2018 to 2025). A tumor composed of atypical neoplastic, often pleomorphic cells that invade other tissues. "The expression of TRIM56 was found to be lower in HepG2.2.15 cells than in immortalized non-cancer HEK293 cells, which have a more intact intrinsic innate immune system." (PMID 41472269, 2025). "In detail, TRIM56 expression was significantly lower in 12 cancer types and significantly higher in 13 cancer types than in normal tissues." (PMID 38348047, 2024). "Previous studies of TRIM56 have suggested that TRIM56 functions as a ubiquitin ligase in regulating cancer progression, due to its RING-finger domain." (PMID 36471347, 2022). "Further work will help identify the cGAS-dependent or -independent functions of TRIM56 in host antimicrobial immunity and cancer." (PMID 29426904, 2018). "Notably, TRIM56 expression was significantly correlated with OS in patients with a total of 6 cancer types, including KIRC, SKCM, STAD, BLCA, LIHC, GBMLGG." (PMID 38348047, 2024). "Notably, some published literature has demonstrated that TRIM56 can target and degrade some oncoproteins, thereby inhibiting the occurrence and development of malignant tumors." (PMID 38463397, 2024). "One of the earliest clues that TRIM56 might be involved in cancer was that TRIM56 is amplified in most primary effusion leukemia (PEL) cell lines and is involved in cell signaling, metabolism and protein maturation." (PMID 36471347, 2022). "Therefore, TRIM56-targeted therapy may address treatment resistance, thereby inhibiting cancer cell proliferation." (PMID 36902478, 2023). "TRIM56, a TRIM family E3 ligase, is crucial for inflammation, innate antiviral responses, and cancer development." (PMID 40756356, 2025). "Interestingly, TRIM56 played a protective role in four cancer types, including KIRC, SKCM, STAD, BLCA, however, it is a detrimental factor for two cancers, including GBMLGG and LIHC." (PMID 38348047, 2024).
bacterial infection (2 papers, 2016 to 2024). "This study gives new evidence for the role of TRIM56 in the innate immune response against intracellular bacterial infection and provides new therapeutic targets for RMSF." (PMID 38358243, 2024). "However, the role of TRIM56 in anti-bacterial infection remains vastly unexplored." (PMID 38358243, 2024). "However, whether TRIM56 participates in the ubiquitination of STING under obligate intracellular bacterial infection is unclear." (PMID 38358243, 2024). "The interactions between SopA and TRIM56 or TRIM65 were verified in transient co-transfection and bacterial infection experiments with epitope-tagged version of these proteins." (PMID 27058235, 2016).
infectious disease (1 paper, 2024). A disorder directly resulting from the presence and activity of a microbial, viral, or parasitic agent in humans. "Importantly, our data suggest that these two activities of TRIM56 can be separated and could inform the development of novel antiviral therapies for infectious diseases." (PMID 38556084, 2024).
metabolic disorders (1 paper, 2025). "Our research has expanded the understanding of TRIM56's role in metabolic disorders." (PMID 39928840, 2025).
TRIM56 also shares sentences with these, for which no sentence is quoted: acute myeloid leukemia (1 paper); alcoholic fatty liver disease (1); Cerebral ischemia (1); dengue (1); diabetic kidney disease (1); endometrial cancer (1); heart failure (1); malignant glioma (1); non-small cell lung carcinoma (1); nonalcoholic fatty liver disease (1); pancreatic cancer (1); prostate carcinoma (1); spinal cord injury (1); spotted fever (1); triple-negative breast carcinoma (1).